BRCA1 (BRCA1 DNA repair associated)
Diseases named in the same sentence as BRCA1 in open-access papers (continued):
Sharing a sentence is not in itself a finding about the gene and the disease.
breast cancer (continued). "In our model, we found that EZN-2208 results in durable responses of ABCG2-expressing BRCA1-deficient mammary tumors, in contrast to topotecan or irinotecan treatment." (PMID 23028879, 2012). "The ectopic expression of BRCA1 is associated with the genesis, progression, and prognosis of young breast cancer patients." (PMID 23276146, 2012). "One important similarity between TNBC and basal-like breast cancer is the incidence of mutations in the breast cancer susceptibility gene 1 and 2 (BRCA1 and 2)." (PMID 22295252, 2012). "We have undertaken the largest analysis of BRCA1 in TN breast cancer to date, and showed that the frequency of BRCA1 mutations in unselected individuals with TN breast cancer is ∼10%, increasing to ∼19% of individuals diagnosed below 50 years." (PMID 22333603, 2012). "Unlike women, BRCA2 germline mutation in men confers a significantly higher lifetime risk of developing breast cancer than BRCA1." (PMID 23146383, 2012). "At the molecular level, the presence of a BRCA1 mutation strongly increases the risk to develop a basal breast cancer." (PMID 22082486, 2012). "Overall, TN cancers account for about 15% of all breast cancers, but occur more frequently in younger women and are the predominant cancer subtype in individuals with a germline BRCA1 mutation." (PMID 22333603, 2012). "This excludes highly penetrant mutations with well-characterized inheritance patterns, such as BRCA1/BRCA2 mutations in breast cancer." (PMID 23071447, 2012). "In our ongoing study of breast cancer predisposition genes in a hospital-based cohort of breast cancer patients, we have analyzed BRCA1 and BRCA2 in all patients younger than 35 years diagnosed with invasive breast cancer." (PMID 22507745, 2012). "It is estimated that 5% to 10% of all breast cancers are attributable to inherited mutations, of which the two most important and highly penetrant are BRCA1 and BRCA2." (PMID 22537934, 2012). "RAD21 is thus a potential BRCA1/2 mutation status-dependent predictive and prognostic marker in familial breast cancers." (PMID 22537934, 2012). "Germline mutations in either one of the two major breast cancer tumour suppressor genes, BRCA1 or BRCA2, confer a 60-85% lifetime risk of breast cancer but explain only around 20% of the breast cancer cases that have a family history of the disease." (PMID 22703186, 2012). "Familial linkage studies have identified high penetrance, low frequency mutations in genes such as the breast cancer susceptibility genes BRCA1 and BRCA2 but these mutations only account for approximately 20% of the familial risk." (PMID 23270421, 2012). "To date, at least 81 large genomic rearrangements in BRCA1 have been identified in high-risk breast cancer families, the majority of which are deletions ranging in size from a few hundred base pairs, to tens of kilobases." (PMID 22347400, 2012). "The BRCA1 E3 ligase activity has been found to be inactivated by a breast cancer-derived mutation and platinum-based drugs." (PMID 23203101, 2012). "We have evaluated the BRCA1 mutation frequency and the implications for clinical practice of undertaking genetic testing in women with TN breast cancer." (PMID 22333603, 2012). "In line with this notion, most breast cancers that occur in women with germline BRCA1 mutations are ER− and PR− and younger BRCA1 carriers were significantly more likely to develop an ER− cancer compared with older carriers." (PMID 22238615, 2012). "Initial findings indicate that neoadjuvant use of cisplatin results in high rates of complete pathological response in patients with breast cancer who have BRCA1 mutations." (PMID 23203101, 2012).
breast cancer (continued). "Germline BRCA1 mutation predisposes early-onset breast cancers that are often triple-negative and that correlate with Basal-like tumors in microarray analyses." (PMID 23173005, 2012). "We have previously identified a BRCA1 or BRCA2 mutation in 2.3% of women with breast cancer using the same study population." (PMID 22455664, 2012). "The largest regional cluster of mutations was found in a breast cancer with a germline mutation in BRCA1, PD4107a, which showed a markedly elevated mutation prevalence over a 14 Mb region on chromosome 6." (PMID 22608084, 2012). "Associations with breast cancer risk, after excluding prevalent breast cancer cases, and BRCA1 mutation class." (PMID 22348646, 2012). "In this study, the expression of the breast cancer susceptibility gene BRCA1 and the tumor suppressor gene WWOX is detected using the immunohistochemical method in young and old female breast cancer patients." (PMID 23276146, 2012). "We have investigated eight novel breast cancer susceptibility loci identified through breast cancer GWAS for their associations with breast cancer risk for BRCA1 and BRCA2 mutation carriers using data from the CIMBA." (PMID 22348646, 2012). "This unexplained familial aggregation of the disease suggests the presence of additional high-risk, breast cancer susceptibility genes, particularly in non-BRCA1/2 families with many cases of early onset breast cancer." (PMID 22703186, 2012). "A rare polymorphism in the SNRPB gene has been associated with reduced risk of breast cancer in BRCA1 mutation carriers." (PMID 22876301, 2012). "Women with a BRCA1/2 mutation face up to an 85% lifetime risk for breast cancer and up to a 65% lifetime risk for ovarian cancer." (PMID 22257650, 2012). "Other loci previously found to be associated with BRCA1 breast cancer risk include the 19p13 and 6q25.1 loci, TOX3 and CASP8." (PMID 22348646, 2012). "In breast cancer, this mechanism contributes to loss of the wild-type BRCA1 allele in inherited disease and to loss of heterozygosity in sporadic cancer." (PMID 22347400, 2012). "The estimated population frequency for BRCA1/2 mutations (0.024 to 0.04%) in recessive and polygenic models, respectively, is held responsible for 5 to10 percent of all breast cancers and 10 to 15 percent of all ovarian cancer risk." (PMID 22984553, 2012). "Tumors bearing mutations of the breast cancer susceptibility genes, Brca1/2, are prone to DNA breakages whose restoration into functional double-strand DNA is Parp dependent." (PMID 23293602, 2012). "We and others have evaluated the impact of reproductive factors in the etiology of BRCA-associated breast cancer, although the results are conflicting and vary by BRCA1 or BRCA2 mutation." (PMID 22405187, 2012). "It is currently accepted that about 5–10% of ovarian cancers and 2–5% of breast cancers have a hereditary background arising in BRCA1/2 genes germline mutation carriers." (PMID 22395474, 2012). "Many tumors, including BRCA1-deficient breast cancers, show an overexpression of genes linked to DNA repair that correlates with chemoresistance and poor prognosis." (PMID 22646717, 2012). "The recognition of the strong association of the TN phenotype and BRCA1 mutations has led to efforts for establishing the frequency of BRCA1 mutations in individuals with TN breast cancer." (PMID 22333603, 2012). "Analysis by tumour ER-status revealed that rs10771399 at 12p11 has a stronger association with ER-negative than ER-positive breast cancer for both BRCA1 and BRCA2 mutation carriers." (PMID 22348646, 2012). "For women with a known BRCA1/2 mutation, breast cancer screening consists of mammography and breast magnetic resonance imaging starting at age 25 years." (PMID 22257650, 2012).
breast cancer (continued). "Two studies reviewed the prevalence of BRCA1/2 mutations in breast cancer patients in terms of ethnic difference, finding that those diagnosed at a younger age (mostly under 35 to 45-year old) had prevalence of 5–10% among various races." (PMID 22382806, 2012). "Discoveries in genetic etiology have been important for the development of novel treatments in other cancers, such as PARP-2 inhibitors in breast cancer patients carrying mutations in the BRCA1 gene." (PMID 23236348, 2012). "Three of the BRCA1 mutations were known breast cancer- associated mutations that were recorded in the Breast Cancer Information Core (BIC) database." (PMID 23110154, 2012). "It is estimated that about 5–10% of ovarian and 2–5% of all breast cancer patients are carriers of a germline BRCA1 or BRCA2 gene mutation." (PMID 22395474, 2012). "Families with history of breast cancer have 50% increased risk of developing ovarian cancer due to germ line mutations in either BRCA1 or BRCA2 tumor suppressor genes." (PMID 22685544, 2012). "Cisplatin and AZD2281 have been shown to cooperate in the treatment of BRCA-1 deficient mammary tumors in vivo, and PARP inhibitors enhance cancer cell sensitivity to radiation and alkylating agents." (PMID 23251575, 2012). "Patients with early onset breast cancer had a variety of BRCA1 and BRCA2 mutations based on the combined risk groups." (PMID 22382806, 2012). "There are specific clinical and pathological features associated with hereditary BRCA1 or BRCA2 mutation associated breast cancers." (PMID 22382806, 2012). "Based on our findings to date, it appears that cumulative sex hormone exposure, particularly estrogen, is likely involved in the development of breast cancer in BRCA1 mutation carriers." (PMID 22405187, 2012). "The prevalence of BRCA1/2 mutations in bilateral breast cancer patients in Korea was 17.7% in our study and was higher than 15.4% prevalence in a previous small study." (PMID 22382806, 2012). "For example, the current cost to comprehensively sequence the breast cancer susceptibility proteins BRCA1 and BRCA2 alone is approximately $4,000." (PMID 25562700, 2012). "Only SNP rs10771399 near PTHLH was associated with breast cancer risk for BRCA1 mutation carriers (per-allele hazard ratio (HR) = 0.87, 95% CI: 0.81 to 0.94, P-trend = 3 × 10-4)." (PMID 22348646, 2012). "In particular, the patients with early onset of less than 35 years of age, bilateral breast cancer, and personal history of breast and ovarian cancer had greater than 10% prevalence of BRCA1/2 mutations." (PMID 22382806, 2012). "Genetic mutations, or altered expression, of BRCA1 correlate with alterations in centrosome number and integrity of the microtubule cytoskeleton observed in breast cancers." (PMID 24278741, 2012). "Women with TN breast cancer diagnosed below 50 years have >10% likelihood of carrying a BRCA1 mutation and are therefore eligible for testing in most centres." (PMID 22333603, 2012). "We undertook BRCA1 mutation analysis in 308 individuals with TN breast cancer, 159 individuals from unselected series of breast cancer and 149 individuals from series ascertained on the basis of young age and/or family history." (PMID 22333603, 2012). "These groups included patients with a family history of breast or ovarian cancers, patients with non-familial breast and ovarian cancer but with other risk factors of genetic disease, and family members of breast cancer patients with BRCA1/2 mutations." (PMID 22382806, 2012).
breast cancer (continued). "It has been shown that in the breast cancers containing mutated BRCA1, a common breast cancer susceptibility gene, changes in the tumor stroma facilitate the malignant transformation of the tumor cells." (PMID 23077482, 2012). "Ethnic variations in breast cancer epidemiology and genetics have necessitated investigation of the spectra of BRCA1 and BRCA2 mutations in different populations." (PMID 22970155, 2012). "Genomic DNA from probands of 44 Ashkenazi Jewish high-risk breast cancer families (wild-type for BRCA1, BRCA2 and CHEK2) was sequenced." (PMID 22347400, 2012). "Cancers were typed for estrogen receptors (ER), progesterone receptors (PR), and HER2, and included nine cases with germline mutations in the breast cancer predisposition genes BRCA1 (five) and BRCA2 (four) (available online)." (PMID 22608084, 2012). "Many centres undertook the screening programme to estimate the prevalence of BRCA1 mutations in breast cancer cases unselected for age and family history of cancer." (PMID 22395474, 2012). "In the 1990s, the two major breast cancer susceptibility genes BRCA1 and BRCA2 were identified revealing that harmful mutations in these genes confer to a cumulative disease risk by age 70 years of 65 and 45%, respectively." (PMID 23226154, 2012). "Some of these responses are altered in breast cancer cells expressing different BRCA1 mutations, in line with previous predictions that mutated forms of BRCA1 will determine tumor cell sensitivity or resistance to different types of chemo- or radiotherapies." (PMID 24278741, 2012). "In CIMBA, we observed an inverse association with the minor allele of rs2180341 and breast cancer risk in BRCA1 mutation carriers (per-allele OR = 0.89, 95%CI 0.80–1.00, p = 0.048), indicating a potential protective effect of this allele." (PMID 22768030, 2012). "The current evidence that the AMPK activator- metformin appears ideally suited for chemoprevention of BRCA1-associated breast cancers is based on retrospective population studies and in vitro observations of the potential mechanism." (PMID 26097796, 2012). "Triple negative breast cancer primarily affects younger women (atypical for breast cancer in general), women with African–American descent and women carrying a BRCA1 mutation." (PMID 22509065, 2012). "In conclusion, this study represents the first evaluation of the deleterious and unclassified genetic variants in the BRCA1/2 genes found in a Lebanese population with a relatively high risk of breast cancer." (PMID 22713736, 2012). "During replication, unrepaired SSB will convert into DSB, and in cells deficient in DSB repair via homologous recombination, e.g., breast cancer cells carrying mutations in BRCA1 and BRCA2, cell death will occur." (PMID 23050241, 2012). "Only a small proportion of breast cancer cases, approximately 5%, are caused by hereditary mutations (such as BRCA1 and 2), with the majority of breast cancers being sporadic or acquired in nature." (PMID 22916092, 2012). "Tomasz found that methylation of the BRCA1 gene in PB DNA correlates with increased risk of breast cancer, suggesting that aberrant methylation of genes in PB and disease predisposition are related." (PMID 23276146, 2012). "Thanks to early multimodal screening, breast cancer in people carrying BRCA1 or BRCA2 mutations can be diagnosed at an early stage, with consequent favorable effects on their survival and quality of life, and also on costs for the health system." (PMID 23171648, 2012). "The minor rs3803662 allele also increased the risk of breast cancer in BRCA1 and BRCA2 carriers as well as in a population-based study of men." (PMID 23270421, 2012). "We therefore tested three further synonymous variants found in breast cancer patients to investigate their effect on BRCA1 splicing." (PMID 22615956, 2012). "About 40–50 % of familial breast cancer can currently be explained by mutations in BRCA1 and BRCA2 genes." (PMID 22544570, 2012).
breast cancer (continued). "Loss of heterozygosity at the BRCA1 locus has been reported in 20%–70% of sporadic breast and ovarian cases and in breast cancers has been correlated with larger tumor size, higher grade, and negative hormone receptor negative status." (PMID 22347400, 2012). "The majority of hereditary breast cancer (HBC) susceptibility can be attributed to germline mutations of to Breast Cancer 1 and Breast Cancer 2 genes (BRCA1 and BRCA2), which are responsible for 30-40% of HBC." (PMID 23217244, 2012). "Germline mutations of the genes BRCA1 (breast cancer 1, early onset) and BRCA2 (breast cancer 2, early onset) are the most common cause of hereditary breast and ovarian cancer." (PMID 22809218, 2012). "A woman’s breast cancer risk increases with a first-degree family history of breast cancer, a Gail risk score of 1.66 or greater, BRCA1/2 genetic mutation, or the presence of atypical hyperplasia." (PMID 22924092, 2012). "The minor allele was statistically significantly associated with a lower breast cancer risk for BRCA1 mutation carriers, (per-allele HR = 0.89, 95% CI 0.80–1.00, p = 0.04)." (PMID 22768030, 2012). "Using a genetically engineered mouse model for BRCA1-deficient breast cancer, we investigated therapeutic strategies to overcome ABCG2-mediated resistance to clinically used topoisomerase I inhibitors." (PMID 23028879, 2012). "At present, the most frequent indications for bilateral risk-reducing mastectomy are high risk histology (such as a typical ductal or lobular hyperplasia and lobular carcinoma in situ), strong family history and positive mutation in the BRCA1 or BRCA2 genes." (PMID 22503188, 2012). "The breast cancer susceptibility gene BRCA1 encodes a phosphoprotein that is involved in ubiquitination, DNA damage response, regulation of cell cycle checkpoints, and transcriptional regulation." (PMID 21407215, 2011). "Genetic analysis identifies the HMMR gene as a modifier of the breast cancer risk associated with BRCA1 gene mutation, while cell biological analysis of the protein product suggests a function in regulating development of the mammary gland." (PMID 22110403, 2011). "A recent study using registry data from Poland identified 102 women who carried a BRCA1 founder mutation and had undergone neoadjuvant chemotherapy for breast cancer." (PMID 21771338, 2011). "Women with a known family history of breast cancer, or of a predisposing gene mutation such as BRCA1 or BRCA2, have a cumulative lifetime risk of 45–65%, and a significant number of these cancers are diagnosed before the age of 50 years." (PMID 21326245, 2011). "We have leveraged the power of massively parallel RNA sequencing to interrogate the transcriptomes of BRCA1-mutated breast cancer cell lines and tumors for putative gene fusions." (PMID 22032724, 2011). "The relatively low concentrations that produced the individual drug sensitivities combined with the synergism in Brca1-/- MMECs provides strong preclinical evidence for the cisplatin-gemcitabine combination in the treatment of BRCA1-associated breast cancers." (PMID 21771338, 2011). "Patients were 810 women, with stage I or II breast cancer, for whom a BRCA1 or BRCA2 mutation had been identified in the family." (PMID 21487411, 2011). "Tamoxifen use was associated with a reduced risk of contralateral breast cancer risk in BRCA1 carriers in the univariate analysis (RR 0.55; 95% CI 0.31–0.94; P=0.03); but not after adjustment for age of diagnosis and the other treatments." (PMID 21487411, 2011). "Basal-like breast cancer, which is associated with mutations in the tumor suppressor gene BRCA1, appears to be more closely related to an EpCAM+ luminal-restricted progenitor cell population." (PMID 21952072, 2011). "Five-to-ten percent of breast cancers occur in women with a deleterious mutation in BRCA1, BRCA2, or other breast cancer-associated genes." (PMID 22312537, 2011).